IL6 (interleukin 6)
Diseases named in the same sentence as IL6 in open-access papers (continued):
Sharing a sentence is not in itself a finding about the gene and the disease.
tumor (continued). "After screening 12 candidate pro-inflammatory-to-anti-inflammatory pairs, only the IL-6/IL-10 mRNA expression ratio in tumor tissues had a significant effect on overall survival (OS) of STAD patients (P = 0.014)." (PMID 36371539, 2022). "Analysis showed that the three selected pro-inflammation markers (IL1B, IL8, IL6) were significantly higher in the Fusobacterium-high tumor samples, suggesting elevated levels of inflammation in these tumors." (PMID 35252868, 2022). "IL-6 can suppress the immune response and support the tumor immune surveillance escape in the TIME of CRC." (PMID 35884974, 2022). "There was a 1.5-fold reduction in the omental tumor burden in anti-IL6 group (P < 0.03), and a four-fold reduction with combination treatment (P < 0.001), compared with control mice." (PMID 35313341, 2022). "In particular, studies in mouse models and in cancer patients have shown that interleukin-6 and -1 (IL-6/IL-1) not only sustain tumor growth, survival and progression, but also perturb host metabolic homeostasis, leading to cachexia." (PMID 35319749, 2022). "In PDAC, at least two different CAF phenotypes, defined based on expression of α-SMA and IL-6, are evident in specific regions in the tumor mass." (PMID 35267539, 2022). "IL-6 is able to diffuse through cells structures and tissues in tumor microenvironment due to its low molecular weight." (PMID 35924148, 2022). "Soluble mediators produced by cancer cells activated tumor-derived MSCs and increased secretion of IL-6, IL-8, (SDF)-1α and expression of CD54 marker." (PMID 35455040, 2022). "For example, a study that mimicked the tumor microenvironment in lung cancer cells showed that the proinflammatory cytokines IL-6 and IL-8 produced in the tumor microenvironment are strong involved autophagy inducers, which supports tumor growth." (PMID 35884904, 2022). "Silencing AGE-1 in GBM decreased the M2 polarization of microglia and secretion of the tumor-supportive cytokines IL-6 and TGF-β1." (PMID 36013403, 2022). "Co-culture of cancer cells and CAFs yielded high concentrations of IL-6, where blocking the IL-6 signaling resulted in decreased tumor growth and increased accumulation of CD8+ TILs in tumor tissues." (PMID 35345849, 2022). "It was found that knocking out tumor IL-6 significantly increased tumor-infiltrating Th cells, significantly increased IFN-γ producing Th1/17, and reduced MDSC recruitment." (PMID 36142210, 2022). "TNF and other inflammatory cytokines that are produced by macrophages in the tumor microenvironment stimulate tumor cells to produce IL-6 and LIF, contributing to tumor growth." (PMID 35740622, 2022). "For this, tumour-bearing mice were treated with 200 μg of anti-IL-6 blocking antibody with the same therapeutic scheme as used for N6L." (PMID 36077801, 2022). "For example, once antigens on the surface of tumor cells are recognized, the tumor cells start to overexpress suppressive cytokines, such as IL6, IL10 or TGF-β, which can block the immune system." (PMID 35624717, 2022). "Immunotherapies, including IL-6 and interferon treatment, are effective in managing CP tumor growth." (PMID 36551172, 2022). "Recent studies have shown that IL-6 plays an important role in tumor progression in terms of tumor cell proliferation, metastasis and drug resistance." (PMID 36104733, 2022). "IL-6 deregulation in tumor cells reprograms the STAT3 pathway in metastatic cells and promotes the recruitment of myeloid suppressor cells and macrophage polarization toward a phenotype that allows tumor cells to escape immune system surveillance." (PMID 36497411, 2022). "It has been reported that IL-6 secreted by tumor-related fibroblasts can inhibit pre-albumin and stimulate fibrinogen, resulting in the decrease of pre-albumin and the increase of fibrinogen." (PMID 35033080, 2022).
tumor (continued). "For example, while IL-6 contributes to carcinogenesis by stimulating proliferation and sustaining chronic inflammation, it has been also found to mobilize anti-tumor T cell immune responses." (PMID 35600164, 2022). "Neutrophils augment tumor progression primarily by promoting the production of interleukin-6 (IL-6), arginase-1 (Arginase-1), and vascular endothelial growth factor (VEGF)." (PMID 35295846, 2022). "To determine the impact of IL-6-induced Glut5 expression on tumor cell proliferation, we established HSC-3 cells with stable Glut5 knockdown using two distinct shRNAs." (PMID 35813468, 2022). "IL-6 has been shown to promote tumor cell growth, invasion, and migration, while IL-8 increases proliferation, angiogenesis, and migration of malignant cells toward blood vessels, thus leading to tumor dissemination." (PMID 35155394, 2022). "This is the first evidence, to the best of our knowledge, that an intrinsic immunosuppressive pathway (IL-6/STAT3) can directly affect tumor antigenicity leading to changes in the T-cell lymphocyte repertoire and restrict antigen dependent tumor immunity." (PMID 36443756, 2022). "The IL-6 in the tumor microenvironment was produced either by the cancer cell or by host stromal cells, or by tumor-infiltrating immune cells, or all of them." (PMID 35406728, 2022). "PERK-mediated upregulation of vascular endothelial growth factor (VEGF), fibroblast growth factor-2 (FGF2), and interleukin-6 (IL-6) and downregulation of anti-angiogenic cytokines significantly promoted tumor growth." (PMID 35269473, 2022). "Tumor-derived small extracellular vesicles (SEVs) induce pro-inflammatory cytokine expression and PD-L1 upregulation in M0 macrophages through IL-6/STAT3 and TLR4 signaling pathways, contributing to an immunosuppressive microenvironment." (PMID 36365103, 2022). "MiR-21 in exosomes or extracellular vesicles induced by GBM tumor cells can be incepted by GAMs and upregulate IL-6, TGF-β, and Arg-1 in M2 GAMs, resulting in downregulating the immune response and accelerating growth and invasion of GBM tumor cells." (PMID 35572545, 2022). "IL-6-mediated STAT3 activation in the tumor microenvironment and cancer cells is associated with tumor cell proliferation, angiogenesis and metastasis." (PMID 35844550, 2022). "Critical growth factors and cytokines, including IL-6, IL-11, IL-22, HGF, and EGF, in addition to oncogenic tyrosine kinases such as c-Met and Src, cause STAT3 dependent activation of tumor growth." (PMID 35327456, 2022). "In the current study, laminin α5 was found overexpressed in tumor tissues of patients with osimertinib resistance and high plasma IL-6 levels, as well as in osimertinib-resistant cell lines with high IL-6 levels." (PMID 35197546, 2022). "We concluded that tumor-derived exosomes recapitulate the Lin28B-induced immune-suppressive pre-metastatic niche, which can be counteracted by PD-L2 and IL-6 elimination." (PMID 35173168, 2022). "This study comprehensively demonstrated that suppression of IL-6 signaling sensitizes tumor cells to hormone therapies, suggestive of the potential therapeutic benefits of IL-6/STAT3 inhibition in luminal, hormone-dependent breast cancers." (PMID 35053592, 2022). "This analysis revealed increased inflammatory response, EMT, hypoxia, IL-6 signaling, and tumor microenvironment pathway expression, which were related to chemoresistance." (PMID 35267605, 2022). "On the other hand, the literature has indicated that endothelial cells secret IL-6 that leads to tumor growth enhancement." (PMID 35986321, 2022). "Tumor-derived factors (such as IL-6, IL-10, and VEGF) impede DC maturation and, as a result, their ability to serve as APCs." (PMID 36703982, 2022). "For example, a report showed that macrophages produced higher levels of TNF, IL6, and IL‐1β after stimulation with H. capsulatum, whereas a different report showed that macrophages treated with dying tumor cells exhibited M2 phenotype." (PMID 35037422, 2022).
tumor (continued). "Attenuation of STAT and IL-6 signaling decreased tumor driving properties of conditioned medium from inflamed sites." (PMID 35681714, 2022). "Noteworthy, previous works in other tumor types identified the RAS pathway as an essential driver of IL6 expression." (PMID 35619118, 2022). "Our previous studies demonstrated that IL-6 in tumor microenvironment (TME) is closely related to the growth of DLBCL." (PMID 36104733, 2022). "Mature DCs then secrete numerous pro-inflammatory cytokines, including tumor necrosis factor-α (TNF-α) and interleukin-6 (IL-6), controlling anti-tumor immune responses." (PMID 35692783, 2022). "As an inflammatory factor, IL6 is produced by tumor cells in the bone microenvironment through autocrine and paracrine." (PMID 35872837, 2022). "Colon cancer cell-derived LIF can regulate the expression of other cytokines, such as granulocyte-colony stimulating factor (G-CSF) and IL-6, to promote tumor progression." (PMID 35740622, 2022). "IL-6 overexpression is manifested by aberrant activation of STAT3 in tumor tissue, leading to decreased E-cadherin and increased vimentin protein expression." (PMID 36291659, 2022). "Further to this, IL-6 is implicated in the activation of JAK-STAT 3 pathway, which is associated with tumour growth and chemoresistance." (PMID 35645374, 2022). "By contrast, RT prevented tumor-induced elevation on IL-6 plasma concentration and oxidative damage markers on skeletal muscle, which attenuated STAT3 phosphorylation, all events that play a key role in skeletal muscle protein degradation." (PMID 35847939, 2022). "Expression of the iCAF markers Il6, Cxcl1, and Lif was markedly elevated in hypoxic PSCs cocultured with tumor organoids relative to their normoxic counterparts." (PMID 36109493, 2022). "As such, increased levels of IL-6 in tumor tissue and IL-17 in peritumoral cells correlated with impaired OS and DFS in patients with iCCA." (PMID 35205774, 2022). "The inhibition of IL-6 signaling reduces inflammation and tumor burden, while also preventing the overgrowth of colitogenic bacteria." (PMID 35625485, 2022). "IL-6 is a multifunctional cytokine participating in cell growth and differentiation, inflammatory reaction, and tumor growth." (PMID 35634509, 2022). "IL-6 displayed downregulation immediately after resection, with further restoration to the level of the primary implanted tumor." (PMID 35884700, 2022). "IL-6 induces metastasis through programming hematopoietic stem and progenitor cells toward tumor-supporting metastatic cells." (PMID 35965580, 2022). "To explore the comprehensive immunological effect of IL-6 on the tumor microenvironment, we analyzed IL-6 levels in immune and stromal cells in clear cell RCC datasets (n = 533) from TCGA." (PMID 36497467, 2022). "It has also been demonstrated that IL-6 can promote metastasis of LC, as IL-6 produced by cancer-cell-activated astrocytes can promote further tumor cell proliferation in the brain of murine models." (PMID 35892857, 2022). "Previous studies have shown that neutrophils, IL-1β, IL-8, and IL-6 were upregulated and lymphocyte, hemoglobin, and IL-12p70 were downregulated in tumor metastasis, which is consistent with our findings." (PMID 36157224, 2022). "Meanwhile, HMGCS2 transcription is negatively regulated by mechanistic target of rapamycin complex 1 (mTORC1) kinase and tumor-derived interleukin-6 (IL-6), presumably suppressing PPARα." (PMID 36432618, 2022). "Due to its effects on tumor progression, metastasis formation, and antitumor immunity, the cytokine IL-6 gained increasing attention and is among the most studied cytokines in the context of LPS." (PMID 36230502, 2022). "IL-6 is a chemokine that is mainly produced in tumors in an autocrine manner by tumor cells and CAFs." (PMID 36422541, 2022). "IL-6 can induce the overexpression of MMP, promote EMT, and activate the MAPK, PI3K/AKT, or JAK/STAT3 pathways to enhance tumor growth and cause chemoresistance." (PMID 35681617, 2022).
tumor (continued). "IL-6 cytokines that derive from the tumor microenvironment combine with the downstream IL-6/STAT3 signal pathway to constitute a central regulator in chemotherapeutic response." (PMID 36439106, 2022). "In our study, the mRNA levels of IL-6 and IL-8 were decreased in the GC group, probably due to the elevated IL-10 level in the local area of the tumor." (PMID 35572666, 2022). "IL-6 trans-signaling not only promotes the malignant proliferation and metastasis of tumor cells but also affects the TME, as well as macrophage M2 polarization." (PMID 36270986, 2022). "Direct enhancement of the production of inflammatory cytokines, such as IL-6 and IL-8, initiates inflammatory processes and facilitates tumor growth." (PMID 36402997, 2022). "Polarized M2 macrophages have been found to regulate tumor cell glycolysis through the secretion of interleukin-6." (PMID 36612063, 2022). "IL-1 (including both IL-1α and IL1-β) and IL-6 stimulate RANKL-induced osteoclastogenesis under inflammatory conditions, but they are also associated with tumor-induced osteoclastogenesis in vitro and in vivo." (PMID 36614130, 2022). "IL-10 can also induce tumor progression by inhibiting many cytokines such as IL-1a, IL-1b, IL-6, IL-8, IL-12, and IL-18." (PMID 35186043, 2022). "TNF-α and IL-6 are critical tumor promotors during tumorigenesis and colonic carcinogenesis in humans and mice." (PMID 35865942, 2022). "In the 100 IU+cal group, the IL-6 plasma concentration was higher in E0771 tumor-bearing mice as compared to C57BL/6 healthy mice." (PMID 36230508, 2022). "The results revealed that mice treated with CM of activated macrophages exhibit higher tumor growth compared to control, whereas the increase in tumor size was abrogated when the IL-6 is neutralized in CM." (PMID 35300689, 2022). "Osteoblasts, osteoclasts, and tumor cells interact with each other, secreting cytokines such as PTHrP, RANK-L, IL-6, and other growth factors that disrupt the normal bone balance and promote tumor growth." (PMID 36230816, 2022). "High IL-6 and Sox4 expression was closely related to tumor size, TNM stage, and a poorer overall survival." (PMID 35513871, 2022). "TFs of AP-1, regulating TNFα, IL-6 and SELE are implicated as oncogenes or tumor suppressors in many cancers with drug development programs targeting cJun, JunB, JunD, cFos, FosB, Fra1 and Fra2." (PMID 36371231, 2022). "Apart from FasL, cytokines such as IL-10 and IL-6, have been demonstrated to play important roles in immunosuppression and promote tumor growth." (PMID 36387244, 2022). "These IR-tEVs in turn elicit enhanced pro-tumor activity of fibroblasts in the form of enhanced IL-6 production, induced radioresistance of breast cancer cells, and the expansion of a cancer stem-like cell (CSC) population." (PMID 36106109, 2022). "AIRE+ prostate cancer cells were shown to secrete increased levels of IL-6 and prostaglandin 2 (PGE2), which polarized the tumor-associated macrophage toward the M2 phenotype with an increased expression of CD206 and CD163 antigens." (PMID 35634292, 2022). "In contrast, Beff cells produce proinflammatory cytokines, including IL-6, IFNγ, and tumor TNFα, to stimulate memory and memory effector CD4+ T cell responses." (PMID 35267563, 2022). "Our results suggest that docetaxel-treated MSL TNBCs initiate an autocrine IL-1A circuit to promote tumor production of IL-6." (PMID 35260569, 2022). "Several biomakers has been reported to be as diagnostic and prognostic biomarkers of fibrosing ILD, including Krebs von den lugen-6 (KL-6), Surfactant proteins A and D (SP-A and SP-D), serum interleukin 6 (IL-6) levels and tumor markers." (PMID 35987772, 2022). "The amount of IL-6 released in the high tumor burden group was significantly higher than that released in the low tumor burden group (P = 0.0427)." (PMID 35013456, 2022). "Elevated IL6 levels in CRC patient serum or tumor tissue were correlated with advanced stages and a poor prognosis." (PMID 36713567, 2022).
tumor (continued). "Our systematic review focusses on the well-described pro-inflammatory cytokine IL-6, known to be important in inflammatory, infectious and neoplastic diseases of multiple organ systems and previously shown to be produced in the brain in response to TBI." (PMID 35790656, 2022). "Natural killer activity against tumor targets was estimated using peripheral blood mononuclear cells (PBMC); to determine circulating IL-6 in plasma, samples of the enzyme linked immunosorbent assay (ELISA) were used." (PMID 36231913, 2022). "The supernatant of collected tumours was analysed by ELISA, and the amount of IL-6 was normalized by the tumour volume and expressed as pg of IL6 in mm2 of the tumour." (PMID 36077801, 2022). "Previous reports showed that IL-6 and IL-8 played an important role in promoting tumor progression in TME." (PMID 36465391, 2022). "After local production by tumor cells in the inflammatory niche, IL-6 is released into the bloodstream and eventually reaches the liver, where it has several biological effects on hepatocytes." (PMID 36072935, 2022). "In NSCLC, IL-6 signaling also promotes the upregulation of DNA repair-related and antiapoptotic genes, thereby enhancing tumor cell resistance to cisplatin." (PMID 35356749, 2022). "IL-6 secreted by dysfunctional adipocytes recruits macrophages in the AT, which leads to an inflammatory response in the AT, and IL-6 derived from tumor tissue plays an important role in the M2-subtype polarization of macrophages in peritumoral tissue." (PMID 36233285, 2022). "In tumors, OSM and other members of the IL-6 cytokine family can exhibit indirect pro-tumorigenic effects affecting the tumor microenvironment and stromal cells and modulating inflammatory and immune responses." (PMID 36077744, 2022). "It has been observed that blocking of the IL-6/IL-8 cytokine signaling leads to decrease in tumor growth." (PMID 35800881, 2022). "IL-6 plays a central role in boosting immunosuppressive MDSC cells in the tumours, and MDSCs in turn are able to regulate Treg differentiation." (PMID 36077801, 2022). "Our findings are in line with studies demonstrating a role of CXCL-1, IL-6 and IL-8 in tumor cell migration and metastasis in other tumor entities." (PMID 35628911, 2022). "Collectively, IL-6 is considered to be a pivotal tumor promoter in colitis-associated cancer and STAT3 is essential for the transduction of tumor-promoting signals from IL-6." (PMID 36135048, 2022). "The same research team proposed that SCs are activated through various routes, notably through hypoxia, tumour-derived interleukin (IL)-6, and chemokine CXCL-12, overexpressed in the pancreatic intraepithelial neoplasia (PanIN)." (PMID 35269454, 2022). "Because chemoattractants are among the mechanisms that regulate immune cell tumor infiltration, we note that certain secreted molecules—including IL-6 and IL-8—are dependent on cancer cell density in the tumor." (PMID 35385679, 2022). "IL-6 favors angiogenesis and tumor vascularization via VEGF secretion, inhibits oxidative stress and DNA damage related to cancer treatment by stimulating antioxidant and anti-apoptotic pathways, and contributes to cancer-related cachexia." (PMID 36298472, 2022). "For example, interleukin-6 (IL-6), a common pro-inflammatory factor, promoted tumor cell proliferation, invasiveness, and metastasis, and affected the clinical prognosis in various solid malignancies including gastric cancer." (PMID 36371539, 2022). "According to previous reports, tumor cells secrete interleukin-6 (IL-6) to stimulate thrombopoietin production at the tumor site, which in turn promotes megakaryocytopoiesis and thrombopoiesis." (PMID 36330089, 2022). "This “hijacking” of pro-tumor-immune cells is mediated immunologically by interleukins (IL) such as IL-6, platelet-derived growth factors, notch-signaling pathways, vascular endothelial growth factor (VEGF), or epidermal growth factor (EGFR)." (PMID 34687436, 2022).